AQP1 (aquaporin 1 (Colton blood group))
Diseases named in the same sentence as AQP1 in open-access papers (continued):
Sharing a sentence is not in itself a finding about the gene and the disease.
brain tumors (15 papers, 2002 to 2025). "On the other hand, increased levels of AQP1 have been associated with a poorer prognosis in brain tumors, prostate adenocarcinoma, lung adenocarcinoma, and carcinomas of the gastrointestinal tract." (PMID 33807998, 2021). "For instance, the occurrence of brain tumors is often associated with the expression of AQP1." (PMID 40760228, 2025). "Of note, AQP1 is expressed in brain tumors, which show similar findings to those of other tumors and warrants more detailed discussion." (PMID 35847914, 2022). "It is, therefore, possible that the anti-brain tumour oedema action of glucocorticoids is at least partly explained by alterations in AQP1 expression." (PMID 12237771, 2002). "In brain tumors, AQP1 and AQP4 expression is upregulated with the malignancy grade." (PMID 38476871, 2024). "The signals that induce AQP1 expression in the endothelium of brain tumors remain unclear but might include signals regulating the production and release of VEGF from cancer cells." (PMID 31803626, 2019). "In addition to be responsible for the high vascular permeability and interstitial fluid pressure in tumors of the brain, colon, breast and pancreas, AQP1 was reported to play a key role in the pathogenesis of ALI." (PMID 29492259, 2018). "Based on these observations, many Authors suggested that AQP1 blockers might function as potent anti-brain tumor edema agents." (PMID 27367682, 2016). "The ability of cells to transport excess H+ from intracellular to extracellular space may also require movement of H2O in the same direction, suggesting another potential function for AQP1 in brain tumours, besides to contribute to vasogenic edema formation." (PMID 21119878, 2010). "In brain tumours AQP1 expression increases with the grade of malignancy." (PMID 21119878, 2010). "Assuming that AQP1 protein is functional in brain tumours, AQP1 may be contributing to the flow of oedema fluid through the tissue." (PMID 12237771, 2002). "The signals that induce AQP1 expression in the endothelium of brain tumours are unknown, but might include vascular endothelial growth factor, which is produced by tumour cells and is known to increase vascular permeability." (PMID 12237771, 2002). "AQP1 may participate in the formation of brain tumor oedema." (PMID 35847914, 2022). "The signals that induce AQP1 expression in the endothelium of brain tumors are, however, still not completely understood, but might include production and release from cancer cells VEGF, which can in turn increase vascular permeability by stimulating BCEC proliferation." (PMID 27367682, 2016). "AQP1 water channel blockers might thus be potent anti-brain tumour oedema agents." (PMID 12237771, 2002). "However, little is known about AQP1 expression in normal human brain and human brain tumours." (PMID 12237771, 2002). "Several studies suggested a crucial role of AQP1 and AQP4 in the vascular permeability of edematous brain tumors." (PMID 35847914, 2022). "In particular, aquaporin-1 (AQP1) is important in tumour growth and spread and AQP4 protein has a crucial role in vasogenic oedema that increases the mortality related to brain tumours." (PMID 36071478, 2022). "AQP1 is expressed in tumour microvessels, where it seems to contribute to increased BBB water permeability in aggressive brain tumours." (PMID 21119881, 2010). "Further studies are needed to clarify the mechanisms responsible for the upregulation of AQP1 (present study) and AQP4 expression in brain tumours and the contribution of these water channels to brain tumour oedema." (PMID 12237771, 2002). "Brain tumour models comparing wild-type mice with AQP1 and AQP4 knockout mice may shed light on the contribution of these water channels to brain tumour oedema." (PMID 12237771, 2002).
brain tumors (continued). "Interestingly, in the promoter of AQP1 gene, steroid responsive elements are present, which could be responsible for regulation of AQP expression and, in turn, for the anti-brain tumor edema action of glucocorticoids." (PMID 27367682, 2016). "AQP1 is expressed in brain capillary endothelial cells from brain tumours that are not surrounded by astrocytic end-feet, suggesting that the latter may signal adjacent endothelial cells to switch off its expression." (PMID 21119881, 2010).
glaucoma (15 papers, 2010 to 2025). Increased pressure in the eyeball due to obstruction of the outflow of aqueous humor. "In this study, we developed a targeted therapy for glaucoma by knocking down two genes associated with aqueous humor production (aquaporin 1 [AQP1] and carbonic anhydrase type 2 [CA2]) using Cas13 RNA editing systems." (PMID 40575705, 2025). "In the context of glaucoma therapy, the CasRx system predominantly focuses on the RNA‐level knockdown of aquaporin 1 (Aqp1), β2‐adrenergic receptor (Adrb2), and Rho‐associated kinase 1/2 (Rock1/Rock2)." (PMID 40536333, 2025). "AQP1 gene polymorphism was assessed in primary open-angle glaucoma, and hypomethylation of the AQP1 gene was indicated in salivary gland adenoid cystic carcinoma." (PMID 24817884, 2014). "Next, we evaluated the therapeutic effect on glaucoma using the CasRx system to interfere with the expression of the Rock1 and Rock2 genes, as well as the Aqp1 and Adrb2 genes, on two simulated glaucoma model mice." (PMID 39080269, 2024). "Here, the authors show that AAV-delivered CasRx to reduce the expression of Rock1 and Rock2 as well as Aqp1 and Adrb2 can significantly reduce intraocular pressure, ultimately delaying glaucoma progression in mice." (PMID 39080269, 2024). "Using two different mouse models of glaucoma, we show that reducing the expression of Aqp1 and Adrb2 in the CB or Rock1 and Rock2 in the TM, significantly reduces IOP, protects retinal RGC cells and delays disease progression." (PMID 39080269, 2024). "An advantage over standard gene therapy is that Aqp1 is a universally expressed protein and its DNA sequence is expected to be broadly conserved among all individuals with glaucoma." (PMID 31981492, 2020). "In addition, we investigated the impact of suppressing the Aqp1 and Adrb2 genes on glaucoma treatment." (PMID 39080269, 2024). "Efficient aquaporin 1 (Aqp1) disruption by CRISPR/Cas9 in the mouse ciliary body epithelium following intravitreal injection is able to lower IOP and prevent RGC loss in a micro-bead glaucoma mouse model." (PMID 35652098, 2022). "Hence, due to the numerous important roles of AQP1 in physiology, selective inhibitors of AQP1 may provide novel treatment opportunities for a variety of human disorders, such as glaucoma, brain edema, and even certain types of tumor growth." (PMID 30972964, 2019). "We demonstrate that hfCas13d-mediated knockdown of AQP1 and CA2 significantly lowers IOP in wild-type mice and in a corticosteroid-induced glaucoma mouse model." (PMID 40575705, 2025). "By selectively disrupting Aqp1 in the adult mouse eye, IOP can be reduced from normal physiological baseline or when elevated in experimental models of glaucoma." (PMID 31981492, 2020). "We also address the hypothesis that during the early stages of glaucoma, increased humous levels of ET‐1 mediates trabecular meshwork tissue remodelling, and we discovered a novel function of ATF4 in controlling the process of TM remodelling through transcription suppression of AQP1 in POAG." (PMID 32052937, 2020). "Nor are the other aquaporins (AQP1 and AQP9) found at the UON region, which is the site of injury to retinal ganglion cell axons in glaucoma." (PMID 33529207, 2021).
Sepsis (15 papers, 2013 to 2025). Sepsis is defined as life-threatening organ dysfunction caused by a dysregulated host response to infection. "H19 acted as a competitive endogenous RNA (ceRNA) for AQP1 by regulating miR-874, reversing LPS-induced inflammatory responses and myocardial dysfunction, suggesting H19 as a potential therapeutic target for sepsis-associated myocardial dysfunction." (PMID 39544938, 2024). "In sepsis, miR-133a-3p downregulates AQP1, resulting in increased expression of inflammatory cytokines." (PMID 39941100, 2025). "Another study investigated the relationship between AQP1, miRNA-874 and lncRNA H19 in LPS-induced sepsis." (PMID 39544938, 2024). "A study of leukocytes in the blood of ICU patients with sepsis showed that AQP1 was induced to be upregulated in leukocytes of ICU patients with acquired sepsis, resulting in higher AQP1 expression in leukocytes of patients with septic shock." (PMID 39238634, 2024). "AQP1 was induced in the leukocytes of patients with ICU-acquired sepsis and exhibited higher expression in septic shock." (PMID 39768394, 2024). "The leukocyte AQP1 expression levels were measured in critically ill patients on ICU admission upon diagnosis of sepsis, and at the occurrence of septic shock." (PMID 39768394, 2024). "AQP1 thus modulates immune responses and indicates PI3K as a pivotal pathway in AQP1-mediated macrophage polarization during sepsis-induced AKI." (PMID 39544938, 2024). "Sepsis-induced endothelial damage and oxidative stress can reduce AQP1 levels, leading to impaired fluid clearance." (PMID 39768394, 2024). "In another study, reduced H19 and AQP1 expression, coupled with increased miR-874 levels, were observed in sepsis patients, a lipopolysaccharide (LPS)-treated mouse model and in cell culture." (PMID 39544938, 2024). "It was consistent with the results of our study that AQP1 protein have a trend of first increasing and then decreasing in renal tissue and serum in AKI with sepsis, while AQP1 mRNA decreased significantly." (PMID 39238634, 2024). "It was found that H19 and AQP1 expressions decreased while miR-874 expression increased in sepsis samples, mouse models and cardiomyocytes." (PMID 39544938, 2024). "Altered expression of AQPs, such as AQP1, AQP3, and AQP5, correlates with sepsis severity, and polymorphisms in AQP5 have been linked to better survival rates and improved outcomes in sepsis-related acute respiratory distress syndrome (ARDS)." (PMID 39544938, 2024). "Another study using a CLP-induced sepsis rat model, myocyte enhancer factor overexpression was found to alleviate acute lung injury by up-regulating AQP1 expression." (PMID 39544938, 2024). "In sepsis, AQP1, AQP4, AQP5, and AQP9 have been shown to significantly affect organs like the brain, heart, lungs, kidneys, and liver." (PMID 39544938, 2024). "lncRNA H19 significantly reverses sepsis-induced inflammatory response and myocardial dysfunction through miR-874/AQP1." (PMID 36274974, 2022). "As a therapeutic option it was demonstrated that hydrogen rich saline and parenteral vitamin C can be protective in sepsis related lung injury and that it can attenuate the LPS induced reduction of Aqp1 and Aqp5 expression." (PMID 29449936, 2018). "We here report the inducible expression of Aqp1 in leukocytes in clinical sepsis and in response to LPS in vitro." (PMID 24028651, 2013).
Sepsis (continued). "Aqp1 is upregulated in leukocytes of critically ill patients with hospital-acquired sepsis, while in vitro studies support triggering by LPS and transcriptional regulation by NF-κB." (PMID 24028651, 2013). "In the context of sepsis, AQP1 overexpression in leukocytes may increase their cell membrane permeability, increasing their volume and, hence, migration." (PMID 39768394, 2024). "Another animal study tested the hypothesis if Aqp1 may play a role in cardiac dysfunction during sepsis." (PMID 29449936, 2018). "• Aqp1 is upregulated in leukocytes of critically ill patients with ICU-acquired sepsis." (PMID 24028651, 2013). "Based on sepsis-specific overexpression, we propose that increased levels of leukocyte Aqp1 may play a role in sepsis." (PMID 24028651, 2013). "However, upon onset of sepsis, we observed a median 1.7-fold (interquartile range: 0.99 to 2.4) increase in Aqp1 mRNA (P = 0.012)." (PMID 24028651, 2013). "Aqp1 mRNA was also measured upon septic shock and was further elevated, corresponding to a median increase of 3.00-fold (interquartile range: 1.20 to 5.40, P = 0.002 from baseline and P = 0.023 from sepsis)." (PMID 24028651, 2013). "We observed an increase in Aqp1 mRNA expression with the appearance of sepsis and septic shock." (PMID 24028651, 2013). "In addition, elevated AQP1 expression was observed in leukocytes of patients with sepsis." (PMID 33567720, 2021). "Based on the findings of the genomic expression analysis of our initial polytrauma patient group, we hypothesized that Aqp1 expression is induced in leukocytes of critically ill patients afflicted with nosocomial sepsis in a manner dependent on sepsis severity." (PMID 24028651, 2013). "This analysis revealed three genes that were commonly dysregulated in both human patients with severe sepsis and ARDS and in experimental models, among them AQP1." (PMID 39768394, 2024). "Another study investigated the role of FGD5-AS1 in sepsis and LPS-induced inflammation and showed that FGD5-AS1 overexpression increased AQP1 and decreased miR-133a-3p expression, subsequently reducing inflammatory cytokines such as TNF-α, IL-6 and IL-1β." (PMID 39544938, 2024). "Similarly, Aqp1 expression decreases following exposure to lipopolysaccharide (LPS) in rat lungs, a reduction that can be counteracted by therapies such as hydrogen-rich saline and parenteral vitamin C, known for their protective effects in sepsis-related lung injury." (PMID 39544938, 2024). "AQP1 and AQP5 expression has been found to be downregulated by numerous investigators in experimental models of sepsis-induced ARDS." (PMID 38203657, 2023). "Therefore, sepsis-induced AQP1 upregulation may impact neutrophil migration and chemotaxis." (PMID 33567720, 2021). "Dual-luciferase reporter and miRNA pull-down assays confirmed that FGD5-AS1 acts as a competitive endogenous RNA for miR-133a-3p on AQP1, suggesting that overexpression of FGD5-AS1 may inhibit the inflammatory response in sepsis." (PMID 39544938, 2024). "Moreover, AQP1 and AQP2 upregulation by various molecules in the setting of sepsis-induced AKI has been shown to suppress the disease’s development." (PMID 38203657, 2023). "Aqp1 expression was indeed detected in human leukocytes by end-point PCR, in patients who either developed sepsis or did not." (PMID 24028651, 2013).
Sepsis (continued). "Furthermore, in cases of ICU-acquired sepsis and SIRS, there is a notable alteration in the expression of AQP1 and AQP9 in leukocytes, which may play a role in cellular responses and plasma membrane dynamics under inflammatory conditions." (PMID 39544938, 2024).
prostate carcinoma (13 papers, 2013 to 2025). A carcinoma that arises from epithelial cells of the prostate gland. "A transcriptomic analysis revealed that increased transcript levels of AQP1 was significantly associated with poor survival of prostate cancer patients." (PMID 36672280, 2023). "Importantly, Rg3 decreased the expression of AQP1 in the PC-M3 prostate cancer cell line, causing the inhibition of the chemoattractant-induced migration of these tumour cells." (PMID 31374984, 2019). "Rg3 inhibited migration of PC-3 M cells, an extremely metastatic prostate cancer cell line, via inhibiting AQP1 expression via the p38 mitogen-activated protein kinases cascade and transcription factors functioning on the AQP1 promoter." (PMID 38336645, 2024). "AQP1 is known to be upregulated by hypoxia that leads to increased cell water permeability, motility, and migration in neuroblastoma, lung and prostate cancer cells." (PMID 36743211, 2023). "Subsequent studies demonstrated that Ginsenoside Rg3 attenuated cell migration via inhibition of AQP1 expression in PC-3M prostate cancer cells." (PMID 36803413, 2023). "Another study examined specimens from benign prostate hyperplasia and prostate cancer and demonstrated that AQP1 is majorly expressed in venules and capillaries of the prostate." (PMID 36672280, 2023). "Also, the channel protein AQP1, which ensures passive transport of water, is induced upon hypoxia in prostate carcinoma cells." (PMID 37671061, 2023). "Studies on structural and functional assessment highlight a strong biological relationship between AQPs protein expression, localization, and key biological functions in normal and prostate cancer tissues, where aberrant AQP1, AQP3 and AQP5 expression correlate with tumorigenesis and metastasis." (PMID 36672280, 2023). "In prostate cancer cells, AQP1 protein expression levels are regulated by p38MAPK." (PMID 35399826, 2022). "Since hypoxia-induced AQP-1 was reported to promote prostate cancer progression, the possible mechanism of AQP-1 upregulation in gastric cancer cells might also through E-box/ChoRE element." (PMID 33209198, 2020). "In contrast, hypoxic stress have been shown to increase expression of another aquaporin isoform, AQP1 in mouse lung and brain, in prostate cancer cell line suggesting the existence of complex tissue specific and isoform specific regulatory circuits for the regulation of aquaporins." (PMID 23469202, 2013). "Taken together, given its small size yet excellent predictive power, we concluded [AQP1, SEPT8, RBM17, TRIM47, VPS25] as a novel, practical biomarker panel for predicting response to 17-AAG treatment in prostate cancer." (PMID 36743211, 2023). "Research investigations found that AQP1 and AQP5 can serve as prognostic biomarker(s) in prostate cancer." (PMID 36672280, 2023). "OncoPrint data analysis of prostate cancer patients further uncovers the possibilities of AQP1, AQP3, AQP5 and AQP9 being developed as prognostic biomarkers for prostate cancer." (PMID 36672280, 2023). "Even though AQPs including AQP1, AQP3, AQP5 and AQP9 have exhibited significant roles that contribute to prostate cancer prognosis, very little progress has been made in identifying AQPs as biomarker(s) for their use in prostate cancer." (PMID 36672280, 2023). "A clinical trial (NCT00851994) was conducted to evaluate the specificity and sensitivity of AQP1 concentration to diagnose the clear cell or papillary renal cell carcinoma (RCC) by comparing urine AQP1 concentrations in RCC, bladder cancer, non-cancer renal masses, and prostate cancer patients." (PMID 36672280, 2023).